POFUT1 (protein O-fucosyltransferase 1)
Description:
Catalyzes the reaction that attaches fucose through an O-glycosidic linkage to a conserved serine or threonine residue found in the consensus sequence C2-X(4,5)-[S/T]-C3 of EGF domains, where C2 and C3 are the second and third conserved cysteines. Specifically uses GDP-fucose as donor substrate and proper disulfide pairing of the substrate EGF domains is required for fucose transfer. Plays a crucial role in NOTCH signaling. Initial fucosylation of NOTCH by POFUT1 generates a substrate for FRINGE/RFNG, an acetylglucosaminyltransferase that can then extend the fucosylation on the NOTCH EGF repeats. This extended fucosylation is required for optimal ligand binding and canonical NOTCH signaling induced by DLL1 or JAGGED1. Fucosylates AGRN and determines its ability to cluster acetylcholine receptors (AChRs).
Synonyms: O-FucT-1; FUT12; KIAA0180; O-FUT; O-Fuc-T; DDD2; OFUCT1
Tractability: Small molecule: a structure with a bound ligand is known. Antibody: UniProt predicts a signal peptide or a membrane-spanning region. PROTAC: ubiquitination databases record sites on it; its protein half-life has been measured.
Gene: Protein-coding gene on chromosome 20 (32,207,851 to 32,238,658, forward strand). Ensembl gene ENSG00000101346.
Subcellular location: Endoplasmic reticulum
Subcellular location (Human Protein Atlas): Centrosome
Pathways (Reactome):
Signal Transduction: Pre-NOTCH Processing in the Endoplasmic Reticulum
Gene Ontology:
Molecular function: peptide-O-fucosyltransferase activity
Biological process: protein O-linked glycosylation via fucose; regulation of Notch signaling pathway; Notch signaling pathway
Cellular component: endoplasmic reticulum; membrane
Genetic constraint (gnomAD): Loss-of-function variants: 16 observed, 37.94 expected, observed/expected ratio (o/e) 0.42, 90% interval 0.28 to 0.64. The upper end of that interval is the gene's LOEUF score, 0.64, which puts it in group 2 of 6, group 1 being the genes least tolerant of losing a copy. Missense variants: 460 observed, 492.93 expected, observed/expected ratio (o/e) 0.93, 90% interval 0.86 to 1.01. Synonymous variants: 204 observed, 204.14 expected, observed/expected ratio (o/e) 1, 90% interval 0.89 to 1.12.
Gene-disease validity (ClinGen):
ClinGen rates the evidence that POFUT1 causes each of these diseases.
Dowling-Degos disease 2 (autosomal dominant): Definitive.
congenital disorder of glycosylation (autosomal recessive): Limited. Congenital disorder of glycosylation (CDG) is a fast growing group of inborn errors of metabolism characterized by defective activity of enzymes that participate in glycosylation (modification of proteins and other macromolecules by adding and processing of oligosaccharide side chains).
Homologues: Orthologues: chimpanzee POFUT1 (100% identical), macaque POFUT1 (98% identical), guinea pig POFUT1 (94% identical), pig POFUT1 (93% identical), dog POFUT1 (92% identical), rat Pofut1 (92% identical), mouse Pofut1 (91% identical), tropical clawed frog pofut1 (69% identical), zebrafish pofut1 (69% identical), Drosophila melanogaster O-fut1 (44% identical), Caenorhabditis elegans pfut-1 (38% identical).
Diseases named in the same sentence as POFUT1 in open-access papers:
POFUT1 is named in the same sentence as 59 diseases in open-access papers, as found by Europe PMC text mining. Sharing a sentence is not in itself a finding about the gene and the disease. The quoted sentences say what the papers report.
colorectal cancer (12 papers, 2017 to 2025). A primary or metastatic malignant neoplasm that affects the colon or rectum. "POFUT1, traditionally associated with the Notch signaling pathway, has been shown to enhance Wnt/β-catenin signaling, especially in colorectal cancer, glioblastoma, and gastric cancer." (PMID 40773107, 2025). "In conclusion, our findings indicate that among the rare missense mutations affecting POFUT1 and found in patients with colorectal cancer, six of them induced an increase of O-fucosyltransferase activity compared to WT POFUT1." (PMID 32486426, 2020). "POFUT1 is an essential enzyme that catalyzes the synthesis of protein O-fucosylation, which has been validated and can be applied as a diagnostic marker of colorectal cancer." (PMID 37251926, 2023). "In colorectal cancer, it has been demonstrated that knocking down POFUT1 in CRC cells significantly reduced their migratory and invasive potentials." (PMID 40773107, 2025). "Several studies demonstrate that in various cancers like glioblastoma, colorectal cancer, and hepatocellular carcinoma, overexpression of POFUT1 promotes cancer cell proliferation." (PMID 40773107, 2025). "PLAGL2 is co-regulated with POFUT1 by a bidirectional promoter, and the two genes synergistically promote tumorigenesis in colorectal cancer by maintaining stemness and cell-cycle deregulation." (PMID 38157850, 2024). "PLAGL2 has been found to be amplified in a small subset of cancers, and has been reported to promote tumorigenesis together with POFUT1 in colorectal cancer." (PMID 36437415, 2023). "Over-expression of amplified genes is partially overlapping with the over-expression of the genes in 20q11.21 amplified clinical samples of colorectal cancer patients, where POFUT1 but also ASXL1, and, in fewer cases, KIF3B and TPX2, are often over-expressed." (PMID 34577783, 2021). "Other genes of the locus with potential pathogenic importance in colorectal cancers, such as TPX2, KIF3B and POFUT1, are also amplified in the 12 cell lines." (PMID 34577783, 2021). "POFUT1 increased the activity of Notch1 signaling pathway and promoted the progression of colorectal cancer." (PMID 34221996, 2021). "ASXL1 is over-expressed in 88.9% of 20q11.21 amplified colorectal cancers in the TCGA cohort, while POFUT1 is over-expressed in 90.5% of 20q11.21 amplified cases in the same cohort." (PMID 34577783, 2021). "A recent study showed that these two genes (POFUT1 and PLAG2) share a bidirectional promoter and, associated with a copy number amplification, promote colorectal cancer through dysregulation of both Notch and Wnt/ß-catenin signaling pathways." (PMID 32486426, 2020). "In conclusion, our findings indicated that POFUT1 is overexpressed in colorectal cancer driven in majority of cases by a 20q11.21 chromosomic region amplification." (PMID 30380753, 2018). "While CNVs are a major driver of POFUT1 overexpression in acute myeloid leukemia and colorectal cancer other mechanisms could also contribute, such as epigenetic control of transcription." (PMID 40773107, 2025). "POFUT1 expression is increased in colorectal adenomas, which are precursors to colorectal cancer." (PMID 38157850, 2024). "These mutated variants could modify the O-fucosylation status of POFUT1 protein targets such as NOTCH1 receptor and its ligands, and subsequently promote colorectal cancer." (PMID 32486426, 2020). "Colorectal cancer is one of the cancers where POFUT1 is the most overexpressed." (PMID 30380753, 2018). "POFUT1 gene is localized in the 20q11.21 region, which is frequently amplified in tumor cells as for breast and gastric cancers, acute myeloid leukemia and colorectal cancer with poor prognosis." (PMID 30380753, 2018). "If it is the case in colorectal cancer, the overexpression of POFUT1 may affect the O-fucosylation state of other proteins." (PMID 30380753, 2018).
colorectal cancer (continued). "In colorectal cancer (CRC), POFUT1 has been more extensively studied and is consistently found to be significantly overexpressed in CRC tissues with a 2.5-fold increase compared to adjacent normal ones, making it a contributor to CRC progression." (PMID 40773107, 2025). "FUT4 is increased in leukaemia, gastric, breast and colorectal cancer; UGT2B17 is increased in endometrial cancer; POFUT1 is increased in glioblastomas and oral squamous cell carcinoma, and MAN2A1 is decreased in glioblastoma." (PMID 30038662, 2018). "Currently, no study focused on the implication of POFUT1 in colorectal cancer, although it is a major public health issue." (PMID 30380753, 2018). "Among these, TM9SF4, POFUT1 and KIF3B are all involved in the pathway of “Colorectal cancer”." (PMID 29108255, 2017).
Dowling-Degos disease (9 papers, 2014 to 2025). A pigmentation disease characterized by a reticulate pattern of abnormally dark skin coloring, particularly in the body's folds and creases. "Mutations in EOGT cause Adams Oliver syndrome and autosomal dominant mutations in POFUT1 cause Dowling Degos Disease 2 (DDD2)." (PMID 37795096, 2023). "Heterozygous deletion mutations in POFUT1 cause Dowling-Degos disease in humans, and the amplification of POFUT1 is related to several types of cancers, including hepatocellular carcinoma, which strongly suggests the biological significance of O-Fuc glycans." (PMID 32825463, 2020). "In addition, a heterozygous missense mutation in the POFUT1 gene is reported to cause the Dowling-Degos disease (DDD) phenotype in multiple Chinese families (OMIM# 615327) as well as one individual from a generalized DDD cohort." (PMID 40725456, 2025). "The distinct effects of O-glycans on Notch receptors, coupled with differential expression of the relevant glycosyltransferases explain why different human diseases arise from mutation of POFUT1 (Dowling-Degos disease), LFNG (Spondylocostal Dysostosis) and EOGT (AOS)." (PMID 28395734, 2017). "Zebrafish have been used to study the development of Dowling-Degos disease (DDD), characterized by hyper and hypopigmentation of the skin around the breast, neck, and groin area due to mutations in POFUT1." (PMID 40725456, 2025). "A recent approach was conducted to determine how POFUT1 missense mutations could impact NOTCH1 signaling (R240A, M262T, S356F and R366W) found in Dowling-Degos disease (DDD), an autosomal dominant genodermatosis." (PMID 32486426, 2020).
hepatocellular carcinoma (8 papers, 2018 to 2025). A malignant tumor that arises from hepatocytes. "Tumors with high POFUT1 levels have a higher histological grade and advanced stage and increased risk of lymph node metastasis in breast, gastric, and hepatocellular carcinomas." (PMID 38157850, 2024). "Besides, POFUT1 overexpression was found in many other cancers and notably in hepatocellular carcinomas, where it was associated with a poor prognosis." (PMID 32486426, 2020). "The increased quantity of POFUT1 in hepatocellular carcinomas was associated with a poor prognosis." (PMID 32486426, 2020). "POFUT1 is overexpressed in hepatocellular carcinoma (HCC), and its high expression correlates with poor prognosis in HCC patients." (PMID 40286076, 2025). "In this context, a study demonstrated that Caveolin-1 (CAV1) upregulates POFUT1 expression in hepatocellular carcinoma by activating the MAPK signaling pathway." (PMID 40773107, 2025). "In hepatocellular carcinoma, POFUT1 overexpression induced an aberrant activation of NOTCH pathway switching on HES1, which in turn promoted migration and cell proliferation." (PMID 30380753, 2018). "Over the past decade, increasing evidence has linked the dysregulation of human protein O-fucosyltransferase 1 (POFUT1), overwhelmingly through gene overexpression, to tumor progression in multiple cancers, including colorectal, breast, gastric, lung, hepatocellular carcinoma, and glioblastoma." (PMID 40773107, 2025). "In addition, the overexpression of POFUT1 correlates with decreased disease-free survival in hepatocellular carcinoma and glioblastomas." (PMID 38157850, 2024). "POFUT1 is significantly overexpressed in hepatocellular carcinoma (HCC), with around 79% of HCC samples showing a marked increase in POFUT1 mRNA expression." (PMID 40773107, 2025). "Increased expression of POFUT1 and POGLUT1 has been found in several cancers, including brain tumors, hepatocellular carcinoma, colorectal cancer, and oral squamous cell carcinoma." (PMID 35335147, 2022). "Since the cross talk between POFUT1 and NOTCH receptors has been demonstrated in hepatocellular carcinoma and gastric cancer, a Spearman’s correlation coefficient was used to determine their relationships in CRC." (PMID 30380753, 2018). "In hepatocellular carcinoma cells, POFUT1 overexpression promoted the binding of the Notch ligand DLL1 to the Notch receptor, and then activated the Notch signaling pathway, indicating that an aberrantly activated POFUT1-Notch pathway is involved in HCC progression." (PMID 35335147, 2022).
lung carcinoma (4 papers, 2018 to 2023). "According to information found in this database regarding POFUT1, some of these seven residues (R43, T115, D348) were also mutated in other cancers such as uterine cancer (R43C), melanoma (T115A, D348N), and lung cancer (D348Y)." (PMID 32486426, 2020). "Droplet Digital PCR (ddPCR) was used for quantification of the genes (miRs-21, 210, 486-5p, SNHG1, RMRP, FUT8, and POFUT1) in plasma of a development cohort of 64 lung cancer patients and 33 cancer-free individuals." (PMID 29872497, 2018). "We previously developed three microRNAs (miRs-21, 210, and 486-5p), two long noncoding RNAs (lncRNAs) (SNHG1 and RMRP), and two fucosyltransferase (FUT) genes (FUT8 and POFUT1) as potential plasma biomarkers for lung cancer." (PMID 29872497, 2018). "Abnormal protein fucosylation has also been found in lung cancer, with FUT8 and POFUT1 proteins being upregulated in blood and tumor tissue of patients with lung cancer." (PMID 37256139, 2023).
Miscarriage (4 papers, 2019 to 2024). A pregnancy that ends at a stage in which the fetus is incapable of surviving on its own, defined as the spontaneous loss of a fetus before the 22th week of pregnancy. "The study suggests that poFUT1 could be seen as a novel potential diagnostic and therapeutic target for miscarriage." (PMID 31601791, 2019). "Previous studies also demonstrated that poFUT1 expression was decreased in placental villi from miscarriage patients and silencing poFUT1 suppressed the proliferation and invasion of JAR cells through inactivating MAPK and PI3K/Akt-signaling pathways." (PMID 32751869, 2020). "Based on the observations of angiogenesis changes and poFUT1 expression in the uterine tissues from menstrual cycle, early pregnancy and miscarriage, we further explored the role of poFUT1 in the angiogenesis and vascular remodeling using hESCs." (PMID 31601791, 2019). "Our previous results also demonstrated that poFUT1 expression was decreased in placental villi from miscarriage patients, and silencing poFUT1 suppressed the proliferation and invasion of JAR cells through inactivating MAPK and PI3K/Akt-signaling pathways." (PMID 31601791, 2019). "The poFUT1 levels in stromal cells were higher in the secretory phase of the menstrual cycle than in the proliferative phase, whereas the poFUT1 levels were lower in the secretory stromal cells of miscarriage patients than in the proliferative phase." (PMID 39062484, 2024). "Previous studies showed that, the expression of poFUT1 was higher in the endometrium of women during the secretory compared to the proliferative phase and in the endometrium of early pregnant women than in that of miscarriage patients." (PMID 32751869, 2020). "Our findings are essential in that they identify early markers (poFUT1 and epiregulin) of miscarriage in serum and trophoblastic cells, which may serve as new biomarkers for clinical diagnosis and provide the foundation for strategies of infertility treatment." (PMID 31889361, 2020). "Additionally, poFUT1 was decreased in the uterine endometrium of miscarriage patients compared with that in early pregnant women." (PMID 31601791, 2019). "We found that the expression of poFUT1 was higher in the uterine endometrium of secretory phase than that of the proliferative phase in the uterine endometrium, and poFUT1 levels were also higher in the decidual of early pregnant women decidua than in that of miscarriage patients." (PMID 31601791, 2019). "Additionally, the expression of poFUT1 was increased in the uterine endometrium during the secretory phase compared with that in the proliferation phase, and its expression was decreased in the uterus of miscarriage patients compared with that of the healthy pregnancy women." (PMID 31601791, 2019). "Additionally, the expression of poFUT1 increased in the uterine epithelium of the secretory phase compared with that in the proliferation phase, whereas this expression was decreased in the uterus of miscarriage patient compared with that in healthy pregnancy women." (PMID 31601791, 2019).
breast carcinoma (3 papers, 2018 to 2025). "In breast cancer, an overexpression of POFUT1 and NOTCH1 was associated with lymph node metastasis and advanced tumor stage." (PMID 30380753, 2018). "In breast cancer, especially in invasive ductal carcinoma, high POFUT1 levels detected by IHC are statistically associated with more aggressive tumor characteristics such as lymph node metastasis and high histological grade (tumor grade 3 versus grades 1 and 2)." (PMID 40773107, 2025). "High expression of POFUT1 mRNA was found to be associated with poor prognosis, including both shorter overall survival (OS) and recurrence-free survival (RFS) in breast cancer patients." (PMID 40773107, 2025). "We found that only FUT8, not FUT3, FUT11, POFUT1, or POFUT2, was closely and positively correlated with B7H3 in breast cancer tissues." (PMID 33976130, 2021).
gastric cancer (3 papers, 2018 to 2025). A primary or metastatic malignant neoplasm involving the stomach. "In gastric cancer, increased POFUT1 expression is associated with some clinical features such as higher TNM staging and tumoral differentiation states." (PMID 30380753, 2018). "In gastric cancer, increased POFUT1 expression is associated with some clinical features, such as higher tumor-node-metastasis (TNM) staging and tumor differentiation states, indicating that POFUT1 might act as a potential biomarker in gastric cancer." (PMID 35335147, 2022). "For gastric cancer, overexpressing POFUT1 enhances both tumor growth and metastasis, with higher NICD levels and an additional synergistic effect with the Wnt pathway." (PMID 40773107, 2025). "In gastric cancer, IHC analysis revealed detectable POFUT1 levels in 64% of the samples, with significantly higher levels compared to adjacent normal tissues." (PMID 40773107, 2025). "Knockdown studies in colorectal, glioblastoma, and gastric cancer models have shown that reducing POFUT1 expression significantly decreases cleaved NICD levels, leading to lower expressions of HES1 and HEY1 and reduced tumor cell proliferation and invasion." (PMID 40773107, 2025). "In gastric cancer, transwell migration and invasion assays were used to compare the behavior of POFUT1 overexpressing cells with control ones." (PMID 40773107, 2025).
glioblastoma (3 papers, 2018 to 2025). The most malignant astrocytic tumor (WHO grade IV). "For glioblastoma, POFUT1 knockdown reduces tumor volume and weight linked to decreased Notch activation (lower NICD, HES1, and HEY1 levels)." (PMID 40773107, 2025). "In cancers like oral squamous cell carcinoma (OSCC), glioblastoma (GBM), and head and neck squamous cell carcinoma (HNSCC), overexpression of POFUT1 has also been associated with highly invasive and aggressive tumor behavior." (PMID 40773107, 2025). "High levels of POFUT1 were found in glioblastoma (GBM) tissue, and GBM patients with high POFUT1 expression had a shorter survival rate." (PMID 35335147, 2022). "In glioblastoma (GBM), knocking down POFUT1 in GBM cell lines induces a significant reduction in cell migration and invasion in both wound healing and transwell invasion assays." (PMID 40773107, 2025).